MIR219A2HG (MIR219A2 host gene)
Gene: Long non-coding RNA gene on chromosome 9 (128,392,007 to 128,393,510, reverse strand). Ensembl gene ENSG00000207955.
Gene Ontology:
Biological process: miRNA-mediated post-transcriptional gene silencing
Cellular component: RISC complex